DYRK1A (dual specificity tyrosine phosphorylation regulated kinase 1A)
Diseases named in the same sentence as DYRK1A in open-access papers (continued):
Sharing a sentence is not in itself a finding about the gene and the disease.
microcephaly (continued). "Interestingly, dysfunctional DYRK1A was described to cause an array of disease phenotypes including intellectual disability, speech delay, motor deficits, autism, and microcephaly (DYRK1A-related syndrome)." (PMID 34257281, 2021). "Conversely, human DYRK1A haploinsufficiency causes microcephaly." (PMID 30496304, 2018). "Mnb/DYRK1A and Reps/REPS1/2 physically interact in both Drosophila and human cells, suggesting conservation of this interaction and a potential novel regulatory axis for DYRK1A-related diseases such as microcephaly." (PMID 39271109, 2024). "Next, T21 and its relationship to ASD, microcephaly, Aβ, tau protein and DYRK1A and will be discussed." (PMID 37808474, 2023). "DYRK1A, a gene function prominent in most of the characteristic features related to microcephaly, is highly conserved in the Down Syndrome critical region (DSCR)." (PMID 38179410, 2023). "The microcephaly observed in humans with DYRK1A haploinsufficiency is recapitulated in both Drosophila and mouse heterozygous mutant animals." (PMID 32467234, 2020). "For example, mice hemizygous for DYRK1A have substantial phenotypic defects, including smaller body size, microcephaly, reduced numbers of neurons, abnormal motor function, gait disturbances, and impaired cognitive function." (PMID 32555303, 2020). "Mutations in DYRK1A and TCF4 cause syndromic diseases presenting with microcephaly and intellectual disability." (PMID 28733602, 2017). "Haploinsufficiency of DYRK1A in humans results in microcephaly and ASD, while knockout of Dyrk1a in mice leads to premature death during early development." (PMID 29021890, 2017). "Microarray detected an intragenic microdeletion of DYRK1A in an individual with microcephaly and autism." (PMID 29021890, 2017). "Intriguingly, truncation of DYRK1A results in the stimulation of kinase activity and DYRK1A gene truncations have been found in human microcephaly." (PMID 29615569, 2017). "In this study, we generated a KO zebrafish line for dyrk1aa after the discovery of an intragenic microdeletion of DYRK1A in an individual with microcephaly and autism." (PMID 29021890, 2017). "In this study, we identified a patient with an intragenic deletion in DYRK1A exhibiting microcephaly and autism." (PMID 29021890, 2017). "Haplo-insufficiency of DYRK1A is associated with the development of autosomal dominant mental retardation-7 (MRD7) (OMIM #614104), a syndrome characterized by primary microcephaly, facial dysmorphism, and behavioral problems." (PMID 29615569, 2017). "Genetic studies in mice and man have revealed that haploinsufficiency of DYRK1A can lead to severe disorders of brain development, including microcephaly, as well as a generalized developmental delay." (PMID 28884684, 2017). "We employed targeted KO of the zebrafish DYRK1A orthologue and found that dyrk1aa KO zebrafish exhibits microcephaly and impaired social behavior which is a key representative feature of ASD." (PMID 29021890, 2017). "These individuals, and the 52 cases reviewed from the literature, show the characteristic features of the DYRK1A-related syndrome including global developmental delay, ID, microcephaly, feeding difficulties, and the facial gestalt." (PMID 26922654, 2016). "The microcephaly observed in MRD7 should be a direct consequence of abnormal neuronal progenitor proliferation and differentiation due to the loss-of-function of DYRK1A, and induce delay in brain development." (PMID 27375444, 2016). "Mouse models and truncations of DYRK1A in patients with microcephaly demonstrated that deregulation of DYRK1A activity has severe phenotypic consequences." (PMID 23665168, 2013). "The dysfunction of these interacting proteins may contribute to the shared clinical manifestations of DYRK1A-related disorders (such as short stature, microcephaly, strabismus, and scoliosis)." (PMID 40182141, 2025).
microcephaly (continued). "In humans, DYRK1A haploinsufficiency causes microcephaly, indicating that a 50% reduction in the level of DYRK1A can yield negative functional consequences." (PMID 30496304, 2018). "Recently, two unrelated patients have been identified with prenatal onset of microcephaly, intrauterine growth retardation, feeding problems, developmental delay, and febrile seizures/epilepsy who both carry a de novo balanced translocation that truncates the DYRK1A gene at chromosome 21q22.2." (PMID 18648535, 2008). "Previous studies on global Dyrk1a-haploinsufficient mice reported neurodevelopmental and ASD-related phenotypes, including reduced viability, developmental delay, microcephaly, behavioral deficits, and neuronal and synaptic alterations." (PMID 39633007, 2025). "In this report, we describe a newly affected individual with a heterozygous 21 kb intragenic deletion which involves the last five exons of DYRK1A; the individual exhibits ASD in addition to learning difficulties and microcephaly." (PMID 29021890, 2017). "Although the proportion of the deletion is relatively small, all symptoms—profound ID, absence of speech, epilepsy, microcephaly, growth retardation, and dysmorphic features—are similar to those described in 21q22.12q22.2-deletions which includes DYRK1A." (PMID 33710394, 2021). "This suggests that microcephaly observed in MRD7 results from different impacts of DYRK1A on brain neurogenesis during embryonic and postnatal development, with Dyrk1aC/C brain revealing the impact of DYRK1A on postnatal neuronal morphogenesis." (PMID 34587162, 2021). "Overall the variation in DYRK1A activity may impact the proliferation of progenitors cells, the function of the REST complex, leading to the microcephaly observed in MRD7 while in DS premature differentiation will lead to a reduced pool of mature neurons." (PMID 27375444, 2016).
diabetes (41 papers, 2015 to 2025). "These flavonoid-based inhibitors offer exciting potential for therapeutic intervention in DYRK1A-associated diseases, including cancer, neurodegenerative disorders, and diabetes." (PMID 40723805, 2025). "Chromosome 21 also encodes other proteins, such as BACE2, RCAN1 and DYRK1A, known to be associated with diabetes mellitus phenotypes and potentially contribute to the increased risk of diabetes mellitus." (PMID 38474215, 2024). "In particular, the finding of DYRK1A, a crucial protein kinase that has been implicated as a potential regulator of β-cells, raises its potential application in diabetes." (PMID 34445786, 2021). "Another potentially important molecular actor in the pathogenesis of AD that may be linked to diabetes is DYRK1A." (PMID 36499613, 2022). "Inhibition of DYRK1A expression reduced the synthesis and release of inflammatory factors in keratinocytes caused by a high-glucose environment, which suggested that DYRK1A may be involved in the hyperglycemia-induced inflammatory response in diabetes." (PMID 38461326, 2024). "Furthermore, DYRK1A has been implicated in neurodegenerative processes, certain cancers and regulation of pancreatic β-cell proliferation, suggesting inhibition of DYRK1A as a novel therapeutic strategy in diabetes." (PMID 33339338, 2020). "Harmine and other small molecule inhibitors of the kinase DYRK1A induce human beta cells to replicate and regeneratein vitroandin vivo, and are effective at reversing diabetes in animal models." (PMID 41573826, 2025). "The therapeutic use of DYRK1A-mediated cell cycle regulation was recently extended to other diseases, such as diabetes and myocardial infarction, as DYRK1A inhibition was found to sustain pancreatic beta cells and cardiomyocytes growth." (PMID 38839871, 2024). "The microRNA miR-221-3p inhibits the inflammatory response and promotes skin wound healing in diabetes by targeting DYRK1A expression, thereby regulating the DYRK1A/STAT3 signaling pathway." (PMID 38461326, 2024). "The results showed that the expression level of DYRK1A was increased in the epidermal tissues in diabetes mice compared with normal mice." (PMID 38461326, 2024). "In this study, we used a high concentration of glucose in the cell culture medium to simulate the high-glucose environment of diabetes, and we used specific siRNA to inhibit DYRK1A expression." (PMID 38461326, 2024). "In conclusion, we demonstrated that miR-221-3p inhibited the inflammatory response and promoted skin wound healing in diabetes by targeting DYRK1A expression and then regulating the DYRK1A/STAT3 signaling pathway." (PMID 38461326, 2024). "Our study shows that miR-221-3p regulated the STAT3 signaling pathway by targeting DYRK1A, inhibiting the keratinocyte inflammatory response and accelerating wound healing in diabetes." (PMID 38461326, 2024). "Growing evidence indicates that inhibition of DYRK1A is critical for β cell restoration and confirm that the DYRK1A signaling pathway is deregulated in diabetes." (PMID 37195917, 2023). "Since then, more and more small molecular DYRK1A inhibitors have been found to increase the mass of islet β-cells, thereby alleviating diabetes." (PMID 36676976, 2022). "Dual-specificity tyrosine-regulated kinase 1A (DYRK1A) inhibitors can induce human β-cell proliferation in vitro and in vivo, and show great potential in the field of diabetes therapeutics." (PMID 36676976, 2022). "In the field of diabetes, many breakthroughs have been made in the discovery of DYRK1A inhibitors, including harmine, 5-IT and GNF2877, which can significantly promote the proliferation of rodent and human β-cells." (PMID 36676976, 2022). "In this paper, we will discuss the regulative roles of DYRK1A in islet β-cells and the mechanism of its inhibitors in improving diabetes, and introduce some natural DYRK1A inhibitors that are being studied." (PMID 36676976, 2022).
diabetes (continued). "DYRK1A is expressed in the peripheral organs and has been shown to be related to diabetes phenotypes, while in wild-type mice, a HFD induces insulin resistance, which is not the case in mice overexpressing DYRK1A." (PMID 35681432, 2022). "This review describes recent reports on the initial self-activation of DYRK1A by tyrosine autophosphorylation, the development of DYRK1A inhibitors, and their importance in the treatment of diabetes mellitus (DM)." (PMID 34445786, 2021). "Increasing evidence for the role of DYRK1A in diabetes progression and β-cell proliferation expands the potential for pharmaceutical applications of DYRK1A inhibitors." (PMID 34445786, 2021). "Studies using DYRK1A haploinsufficient mice have confirmed that they are burdened with severe glucose intolerance, reduced β-cell mass, and proliferation, leading to diabetes." (PMID 34445786, 2021). "This review focuses on DYRK1A inhibitors developed for β-cell restoration and treatment of diabetes." (PMID 34445786, 2021). "DYRK1A haploinsufficient mice are characterized by severe glucose intolerance and reduced β-cell mass and proliferation, eventually developing diabetes, but upregulation of DYRK1A in their β-cells only enhances the phenotype." (PMID 34571911, 2021). "Some experts assume that since DYRK1A expression is ubiquitous, DYRK1A inhibitor therapy for diabetes will require conjugation of a DYRK1A inhibitor to a beta cell-specific targeting molecule." (PMID 34335466, 2021). "Numerous studies have previously reported the development of DYRK1A inhibitor scaffolds for a variety of therapeutic applications including diabetes." (PMID 32340326, 2020). "DYRK1A has attracted great attention as a potential therapeutic target because of its role in neurodegenerative diseases, various cancers, and diabetes." (PMID 32957634, 2020). "When applied to human or rodent islets, the DYRK1A inhibitors promote β-cell proliferation, and restore normal blood glucose levels in several mouse models of diabetes." (PMID 27935966, 2016). "Although several DYRK1A inhibitors have been implemented for potential therapeutic use in neurological disorders, cancer, and diabetes, developing a DYRK1A inhibitor that performs selectivity towards beta cells while avoiding adverse reactions is a formidable undertaking." (PMID 40913218, 2025). "Small-molecule pharmacological inhibitors of DYRK1A, such as harmine, are actively being developed for the treatment of diabetes, because they promote expansion of insulin-secreting pancreatic ®-cells and appear well-tolerated in both animal models and human volunteers." (PMID 39896677, 2025). "We hypothesized that miR-221-3p regulates the DYRK1A gene to ultimately promote wound healing in individuals with diabetes." (PMID 38461326, 2024). "The combination of a DYRK1A inhibitor, harmine, together with exendin-4, increases human β cell mass in immunodeficient mice transplanted with human islets by 700% over 3 months of treatment, while also reversing diabetes." (PMID 37195917, 2023). "Notably, overexpression of DYRK1A in peripheral organs was related to diabetes phenotypes, while pharmacological inhibition of DYRK1A leads to an improved glycemic control in both mice and human cells." (PMID 36670973, 2023). "With the recent findings regarding the crucial roles of GSK3β and DYRK1A in diabetes pathogenesis, we believe that the development of potent and selective inhibitors for these targets could be of great importance to treat both T2D and AD." (PMID 36499613, 2022). "The inhibition of DYRK1A could be a promising target to restore islet β-cell dysfunction in diabetics." (PMID 36676976, 2022). "DYRK1A inhibitors have been shown to induce human β-cell proliferation in the 1–3% range, including harmine, INDY, GNF4877, 5-IOdotubericidin (5-IT), CC-401, and others, indicating that DYRK1A inhibitors have great potential to improve diabetes due to their ability to promote β-cell proliferation." (PMID 36676976, 2022).
diabetes (continued). "However, the small molecule toolset available and understanding of DYRK1A inhibition in diabetes is still insufficient." (PMID 34571911, 2021). "Moreover, the importance of developing novel DYRK1A inhibitors and their implications for the treatment of diabetes are thoroughly discussed." (PMID 34445786, 2021). "The protein kinase DYRK1A has important functions in neuronal development and cell cycle control, and has attracted large attention as a possible drug target for treatment of neurodegenerative processes, certain cancers, diabetes, and other diseases." (PMID 33339338, 2020). "Notably, DYRK1A has been proposed as a potential therapeutic target for the treatment of diabetes because of its key role in pancreatic β-cell proliferation." (PMID 32957634, 2020). "In the case of DYRK1A, the search for both naturally occurring and synthetic inhibitors has been extensive given that DYRK1A may be a potential pharmacological target not only in cancer but, also, in neurodegenerative diseases, DS and diabetes." (PMID 32751160, 2020). "It is important to note that this study provides deeper insights into the effects of 7-position modifications of harmine on DYRK1A inhibition in context of diabetes than previously reported, with two novel analogs compounds showing robust β-cell proliferation activity." (PMID 32340326, 2020). "We explore structure–activity relationships of the 7-position of harmine for both DYRK1A kinase inhibition and β-cell proliferation based on our related previous structure–activity relationship studies of harmine in the context of diabetes and β-cell specific targeting strategies." (PMID 32340326, 2020). "Thus, our study showed that miR-221-3p inhibits the synthesis of inflammatory factors in skin wounds generated in an animal model of diabetes and that the infiltration of immune cells such as neutrophils and macrophages is mediated through the DYRK1A/STAT3 signaling pathway." (PMID 38461326, 2024). "In a recent study, a series of 1,5-naphthyridine derivatives for the chemical inhibition of dual specificity tyrosine-phosphorylation-regulated kinase 1A (DYRK1A) have been described, as a promising therapeutic strategy for diabetes." (PMID 32708796, 2020). "Moreover, deregulation of the DYRK1A gene could also be involved in other human pathologies, such as neurodegenerative diseases, diabetes, osteoporosis or cardiac dysfunction, and recent evidence points to a role for DYRK1A in the progression of several types of cancer." (PMID 30979931, 2019). "Challenges like low selectivity, potential off-target effects, and incomplete mechanism insights explain why DYRK1A inhibitors, despite encouraging in vitro and animal model outcomes, have not advanced to clinical trials for diabetes therapy." (PMID 40913218, 2025). "Taken together, these key findings suggest that miR-221-3p may directly inhibit the expression of DYRK1A to regulate the inflammatory response of epithelial tissues mediated by the STAT3 signaling pathway and thus promote skin wound healing in diabetes." (PMID 38461326, 2024). "We present here a non-exhaustive list of studies using GSK3β and DYRK1A inhibitors as therapeutic approaches for diabetes and AD." (PMID 36499613, 2022). "At present, aristolactam BIII has not been studied in the field of diabetes, but its structure–activity relationship can provide an idea for us to develop DYRK1A inhibitors targeting islet β-cells." (PMID 36676976, 2022). "As well as obesity, a number of genes located on the DS critical region of chromosome 21, including dual-specificity tyrosine phosphorylation regulated kinase 1A (DYRK1A) and regulator of calcineurin 1 (RCAN1), are being investigated and are thought to contribute to diabetes in DS." (PMID 36178378, 2022). "Thus, simply combining an oral DYRK1A inhibitor with any one of a variety of approved GLP1R agonists is achievable, cost-efficient and enormously scalable to millions of people with diabetes globally." (PMID 34335466, 2021).
diabetes (continued). "Moreover, it implies that combining inhibitors for both DYRK1A and DYRK1B could potentially offer a comprehensive approach to diabetes treatment, opening new avenues for targeted diabetes therapies that consider both β-cell proliferation and HGP." (PMID 40287828, 2025). "According to current knowledge, DYRK1A and DYRK1B appear to act similarly in cell cycle control and pharmacological DYRK1 blockade might thus be exploited to expand pancreatic β-cell pools in the fight against diabetes." (PMID 39863750, 2025). "In addition, it was reported that EGCG could inhibit DYRK1A with an IC50 of 0.33 mM, while it exhibited low affinity for other kinases in the CMGC family, such as MAPK and GSK3β, indicating its distinct potential against diabetes." (PMID 36676976, 2022). "Notably, a recent study has highlighted the significance and versatility of DYRK1A by showing that inhibition of DYRK1A by harmine increases human pancreatic β-cell proliferation through the modulation of NFAT signaling, indicating a new therapeutic approach for diabetes." (PMID 27483355, 2016).